CBS (cystathionine beta-synthase)
Diseases named in the same sentence as CBS in open-access papers (continued):
Sharing a sentence is not in itself a finding about the gene and the disease.
anemia (2 papers, 2018 to 2025). A reduction in the number of red blood cells, the amount of hemoglobin, and/or the volume of packed red blood cells. "Clearly, the reduced levels of AHCY and CBS were observed in anemia." (PMID 29551975, 2018).
autism (2 papers, 2021 to 2024). Persistent deficits in social interaction and communication and interaction as well as a markedly restricted repertoire of activity and interest as well as repetitive patterns of behavior. "When looking at CBS polymorphism, four autism cases carry a heterozygous (CT) genotype and one joint pain case has a heterozygous (CT) genotype." (PMID 39148948, 2024). "There was a correlation between CBS (C699T) polymorphism and autism in which the T allele was significantly more frequent among Egyptian autism cases compared with controls." (PMID 33712060, 2021).
cardiomyopathy (2 papers, 2016 to 2019). A disease of the heart muscle or myocardium proper. "The antioxidant contribution of H2S in causing regression of LVH is also supported by a recently reported study demonstrating up regulation of CBS in cardiomyopathy." (PMID 26963622, 2016). "A recent report has demonstrated that selective homocysteine lowering potently attenuates pressure overload-induced cardiomyopathy via reduced oxidative stress but highlighted the contribution of the cystathione β synthase (CBS) enzyme in pressure overload cardiac hypertrophy and heart failure." (PMID 26963622, 2016).
cognitive decline (2 papers, 2021 to 2022). "This could lead to increased CBS activity and clearance of Hcy, thus minimizing cognitive decline." (PMID 35276958, 2022).
coronary-artery disease (2 papers, 2022 to 2024). "CA9, CBS, CEBPG, HSPB1, SLC1A4, HSPB1 and TRIB3 are genes that we have screened for iron death in coronary heart disease samples." (PMID 35152560, 2022). "Although the 844ins68 does not seem to disturb the activity of the CBS enzyme, the frequency is increased in people with premature coronary-artery disease." (PMID 38628775, 2024).
dilated cardiomyopathy (2 papers, 2021 to 2022). Cardiomyopathy which is characterized by dilation and contractile dysfunction of the left and right ventricles. "Besides, we also found that CEBPG was closely related to the ‘Regulation of actin cytoskeleton’ (also enriched in SLC1A4, STMN1 and CBS), ‘Vascular smooth muscle contraction’, ‘Dilated cardiomyopathy’, ‘Relaxin signalling pathway’, ‘Cardiac muscle contraction’ and ‘Hypertrophic cardiomyopathy’." (PMID 35152560, 2022).
dyslipidemia (2 papers, 2017 to 2020). "In conclusion, the CBS mutated rabbit model is a promising tool for studying human dyslipidemia, despite their high mortality." (PMID 33054837, 2020). "A CBSG307S rabbit model was generated that exhibited severe dyslipidemia when fed on a normal diet, indicating that G307S mutation in the CBS gene is a causative factor for dyslipidemia." (PMID 33054837, 2020).
dysplastic nevi (2 papers, 2021 to 2024). "On the other hand, the screening of the CBS expression level in the same cohort of patients revealed that CBS was absent in dysplastic nevi." (PMID 38250807, 2024). "An immunohistochemical (IHC) analysis from human samples showed that CSE, CBS, and 3-MST express in normal human epidermal melanocytes, and all the dysplastic nevi were positive for CSE, negative for CBS, and variable for 3-MST." (PMID 33986916, 2021).
E. coli infection (2 papers, 2023 to 2025).
Encephalopathy (2 papers, 2020 to 2021). Encephalopathy is a term that means brain disease, damage, or malfunction. "We systematically evaluated reports from 11 published and 4 unpublished patients with CBS deficiency and from additional four cases of encephalopathy in association with elevated methionine." (PMID 32154053, 2020).
epilepsy (2 papers, 2024 to 2025). A brain disorder characterized by episodes of abnormally increased neuronal discharge resulting in transient episodes of sensory or motor neurological dysfunction, or psychic dysfunction. "Two children (P1, P3) with CBS deficiency had epilepsy, with plasma tHcy levels of 119.6 μmol/L and 227.2 μmol/L, respectively." (PMID 40994713, 2025). "Four diagnostic biomarkers (ALOX12B, CBS, CPT1C, and DAGLB) showed high accuracy for epilepsy diagnosis, with an AUC value of 0.9592." (PMID 38419709, 2024). "Our research identified potential DELMRGs (ALOX12B, CBS, CPT1C, and DAGLB) in epilepsy, which may provide new ideas for studying the pathogenesis of Epilepsy." (PMID 38419709, 2024). "Our research unveiled potential DELMRGs (ALOX12B, CBS, CPT1C and DAGLB) in TSE, which may provide new ideas for studying the psathogenesis of epilepsy." (PMID 38419709, 2024).
folate deficiency (2 papers, 2017 to 2024). A nutritional condition produced by a deficiency of FOLIC ACID in the diet. "For the present study, we identified DNA hypomethylation of CBS promoter induced by folate deficiency and validated putative role of the DNA hypomethylation of cfDNA in patients’ plasma as a potential noninvasive circulating biomarker for CRC." (PMID 28881655, 2017). "Our study showed that DNA hypomethylation in CBS promoter, induced by folate deficiency, would lead to up-regulation of CBS both in vitro and vivo." (PMID 28881655, 2017). "Our results indicated that DNA hypomethylation of CBS promoter induced by folate deficiency could serve as a potential noninvasive circulating biomarker and may be helpful in developing more effective prognostic markers for CRC." (PMID 28881655, 2017). "Our study showed that the long-term folate deficiency could lead to the DNA hypomethylation of CpG islands in CBS promoter, which would then result in up-regulation of CBS." (PMID 28881655, 2017). "Although there have been studies on genetic or epigenetic regulation of CBS and its role in tumorigenesis, to the best of our knowledge there are seldom reported studies on the DNA hypomethylation of promoter and consequent up-regulation induced by folate deficiency in CRC." (PMID 28881655, 2017). "In conclusion, we have described a female patient with a combined vitamin B12 and folate deficiency, housing heterozygous mutations in both the AMN and CBS genes." (PMID 39582727, 2024). "Our results disclosed that folate deficiency decreased the total level of 5-hmC but did not have a significant effect on local 5-hmC level of CBS promoter." (PMID 28881655, 2017). "However, despite folate deficiency can lead to reduce the total level of 5-hmC, our results disclosed that DNA hypomethylation in CBS promoter was mainly caused by folate deficiency but not by the demethylation of 5-hmC." (PMID 28881655, 2017).
gastric tumors (2 papers, 2012 to 2022). "We further demonstrated that loss of CBS cooperates with AKT hyperactivation to promote anchorage-independent growth of gastric epithelial cells and restoration of CBS expression inhibited PI3K/AKT hyperactive gastric tumor growth." (PMID 35758651, 2022). "CBS loss cooperates with activated PI3K/AKT signaling in promoting anchorage-independent growth of gastric epithelial cells, while CBS restoration suppresses the growth of gastric tumors in vivo." (PMID 35758651, 2022). "CBS promoter methylation was detected in 30% of CRC (29/96) and 55% of gastric tumors (11 of 20), but was infrequently found in normal gastric (1/20, 5%) or colon tissue (0/17, 0%) samples." (PMID 23152928, 2012).
gastric ulcer (2 papers, 2013 to 2019). An ulcerated lesion in the mucosal surface of the stomach. "On other hand, our results revealed that Althaea officinalis and Solanum nigrum pretreatments significantly increased CBS and HO-1 activities in comparison to the gastric ulcer control group." (PMID 31731465, 2019). "But, it significantly increased CBS and HO-1 activities to 266.82% and 187.31%, respectively, in comparison to the gastric ulcer control group." (PMID 31731465, 2019). "It significantly increased CBS and HO-1 activities to 271.3% and 230.65%, respectively, in comparison to the gastric ulcer control group." (PMID 31731465, 2019). "We previously observed a marked up-regulation of CSE and CBS expression and a corresponding increase in H2S synthesis at the margins of gastric ulcers, which is the key area of re-epithelialization and angiogenesis that drive ulcer healing." (PMID 23940796, 2013).
gynecological cancers (2 papers, 2022 to 2023).
infertile (2 papers, 2024). "In line with our studies, Wang and Meng reported that in infertile men, especially in patients with asthenospermia, the concentration of H2S in the seminal plasma and the expression of CBS in the sperm have decreased." (PMID 38811647, 2024). "Interestingly, CBS-KO in the uterus itself is not a direct cause of infertility in these individuals." (PMID 38933705, 2024). "It is worth noting that although CBS-KO may lead to reduced fertility or even infertility in female offspring, this is not the case for male offspring." (PMID 38933705, 2024).
lung fibrosis (2 papers, 2024 to 2025). "Since CBS catalyzes the conversion of Hcy to cysteine, we investigated whether its overexpression via adenovirus‐encoded CBS (Ad‐CBS) could reverse lung fibrosis in BLM‐treated mice." (PMID 40990430, 2025). "Overexpression of CBS markedly suppressed BLM‐induced pulmonary fibrosis, underscoring the contributory role of Hcy in fibrogenesis." (PMID 40990430, 2025). "Cystathionine beta-synthase (CBS) has been clearly demonstrated in lung fibrosis and renal fibrosis The increased expression of CBS attenuated TGF-β1-induced ECM deposition in vitro." (PMID 38287425, 2024).
Marfan syndrome (2 papers, 2017 to 2021). A disorder of the connective tissue. "However, at the aged of 27 years, not having a causative mutation for Marfan’s Syndrome in the Fibrillin-1 gene, skin biopsy was performed and confirmed CBS deficiency consistent with classical HCU." (PMID 35342812, 2021).
memory impairment (2 papers, 2014 to 2022). "We are well aware that, in all strains containing a deletion of the CBS gene, the accumulation of toxic neurotransmitter homocysteine may influence the functioning of the nervous system and be at least partially responsible for the observed learning and memory impairments." (PMID 35740876, 2022).
mental disorder (2 papers, 2017 to 2021). A disease that has its basis in the disruption of mental process. "A close association between mutations in several regions of the human CBS gene and mental disorders and vascular diseases has been identified." (PMID 28512446, 2017). "The manifestation of mental disorders (but not schizophrenia) with CBS deficiency has been described for a long time, and in the Russian population, data were obtained on the association of the 844ins68 CBS genetic polymorphism with schizophrenia." (PMID 34707909, 2021).
multiple myeloma (2 papers, 2018 to 2023). "We analyzed single nucleotide polymorphisms (SNPs) in PKNOX1 (rs2839629) and in the intergenic region between PKNOX1 and CBS (rs915854) by Sanger sequencing in 88 patients with multiple myeloma treated with bortezomib." (PMID 37194045, 2023).
myopia (2 papers, 2024 to 2025). "We observed that all patients with CBS deficiency experienced lens ectopia and myopia." (PMID 40994713, 2025).
pancreatitis (2 papers, 2021 to 2022). Inflammation of the pancreas. "H2S, synthesized from L-cysteine by either of the two cytosolic enzymes (CBS and CSE), is considered as a pro-inflammatory factor in several inflammatory diseases, including arthritis and pancreatitis." (PMID 36091585, 2022).
periodontitis (2 papers, 2021). An acute or chronic inflammatory process that affects the tissues that surround and support the teeth. "It was found previously that CBS and CSE were both increased in human gingival tissue during periodontitis through the technology of PCR and Western blot." (PMID 34635770, 2021).
phenylketonuria (2 papers, 2021 to 2023). Phenylketonuria (PKU) is the most common inborn error of amino acid metabolism and is characterized by mild to severe mental disability in untreated patients. "The amino acid mixtures available for CBS deficiency are less palatable than those for other disorders, such as phenylketonuria; this is related to the amino acid composition, such as the need for cystine, but it is clearly something for the medical food industry to work on." (PMID 33691747, 2021).
schizophrenia (2 papers, 2019 to 2021). A major psychotic disorder characterized by abnormalities in the perception or expression of reality. "iPSCs‐derived neurospheres from schizophrenia patients carrying 22q11.2 micro‐deletions showed a significant increase in CBS mRNA compared to those derived from control subjects." (PMID 31657521, 2019). "In the postmortem brain samples, the average methylation levels in the 3′ portion of “CpG227” (examined by probing the interval #17) were higher in the schizophrenia samples than in the controls and exhibited a positive correlation with the expression levels of CBS." (PMID 31657521, 2019). "In human brains, CAT was upregulated in schizophrenia samples compared to the controls (Fig EV5A), and the expression level of this gene was positively correlated with that of MPST and CBS in both the schizophrenia and control samples (Fig EV5B and C)." (PMID 31657521, 2019). "The expression levels of differentially expressed CBS and MPST were well correlated with each other in both the control and schizophrenia brain samples." (PMID 31657521, 2019). "In human postmortem brains [Brodmann area (BA) 8, frontal cortex] (1st sample set), RT–qPCR analyses revealed increased expressions of MPST and CBS in subjects with schizophrenia, with no change in CTH mRNA levels." (PMID 31657521, 2019).
Sepsis (2 papers, 2022 to 2025). Sepsis is defined as life-threatening organ dysfunction caused by a dysregulated host response to infection. "Our data demonstrate that CBS knockdown significantly exacerbates the necroptosis of adrenal tissues and sepsis-induced adrenal dysfunction in mice, whereas exogenous H2S administration effectively reverses these pathological outcomes." (PMID 40430756, 2025). "Previous studies from our lab using lipopolysaccharide (LPS)-induced sepsis models revealed that LPS suppresses the expression of CBS/CSE, which are key enzymes for H2S synthesis, leading to adrenal dysfunction." (PMID 40430756, 2025). "This suggest that the DG treatment may favorably impact the heart in a sepsis condition and that it could restore the redox homeostasis in part by the H2S, CBS, CTH, GSH, and thiol elevations in this organ." (PMID 36293383, 2022).
steatosis (2 papers, 2022 to 2024). Increased lipid within the cytoplasm of cells. "Supporting this correlation, CBS deficiency (CBS −/− mice) alters liver morphology and induce microvesicular steatosis." (PMID 36144184, 2022).
subarachnoid hemorrhage (2 papers, 2024 to 2025). A serious neurological disorder characterized by intracranial hemorrhage into the subarachnoid space. "Indeed, L-cysteine was found to upregulate the expression and activity of CBS and reduce brain edema in rats following a subarachnoid hemorrhage." (PMID 39458952, 2024).
tauopathies (2 papers, 2020 to 2023). "Clinical validity could be limited in tauopathies where the accumulation of tau is expected in regions with a high concentration of MAO-B, like in PSP and CBS." (PMID 32098280, 2020).
ulcer (2 papers, 2013 to 2020). "However, in chronic experimental gastric ulcer study, the daily treatment with CO donor throughout 9 days period, accelerated ulcer healing and upregulated mRNA expression for CTH and CBS increasing H2S production at the gastric mucosa of ulcer margin." (PMID 32183095, 2020).
vascular dementia (2 papers, 2022 to 2025). A degenerative vascular disorder affecting the brain. "In a vascular dementia model, both PAG and AOAA markedly suppressed the effects of remote preconditioning by reducing H2S, CBS, CSE, and Nrf2 expression and enhancing oxidative damage in nervous tissue." (PMID 41465271, 2025).
vitamin D deficiency (2 papers, 2023). A nutritional condition produced by a deficiency of VITAMIN D in the diet, insufficient production of vitamin D in the skin, inadequate absorption of vitamin D from the diet, or abnormal conversion of vitamin D to its bioactive metabolites. "Since the CBS gene is a target of the vitamin D receptor, vitamin D deficiency can increase homocysteine levels by decreasing CBS, inducing increased NK cell cytotoxicity, which in turn further promotes the inflammatory immune response at the maternal–foetal interface and leads to RSA." (PMID 37355665, 2023).
Acute hepatic porphyria (1 paper, 2021). Acute hepatic porphyrias represent a sub-group of porphyrias (see this term) characterized by the occurrence of neuro-visceral attacks with or without cutaneous manifestations. "CBS inhibition results in accumulation of the cardiovascular risk factor homocysteine (Hcy) and evidence is emerging for plasma Hcy elevation in patients with acute hepatic porphyrias." (PMID 34251022, 2021). "The role of haem in the activity of cystathionine β-synthase (CBS) is reviewed and a hypothesis postulating multiple effects of haem on enzyme activity under conditions of haem excess or deficiency is proposed, with implications for some therapies of acute hepatic porphyrias." (PMID 34251022, 2021).
Acute hepatitis (1 paper, 2020). Acute hepatic injury resulting from inflammation typically accompanied by increased serum alanine transaminase activity. "CTH and CBS are also members of the transsulfuration pathway that metabolizes methionine, and homozygous (CTH−/−) knockout mice displayed acute hepatitis in cases of excessive methionine intake." (PMID 32701483, 2020).
amyotrophic lateral sclerosis (1 paper, 2020). Amyotrophic lateral sclerosis (ALS) is a neurodegenerative disease characterized by progressive muscular paralysis reflecting degeneration of motor neurons in the primary motor cortex, corticospinal tracts, brainstem and spinal cord. "On the other hand, H2S production by CBS has been found elevated in amyotrophic lateral sclerosis (ALS) both in mice tissues and cerebrospinal fluid of ALS patients." (PMID 33353117, 2020).
Anxiety (1 paper, 2025). Intense feelings of nervousness, tension, or panic often arise in response to interpersonal stresses. "In contrast, injection of CBS antibody in the hippocampus of adult mice increased anxiety and depressive-like behavior." (PMID 40551819, 2025).
Aphasia (1 paper, 2023). An acquired language impairment of some or all of the abilities to produce or comprehend speech and to read or write. "One year after, this mutation has been reported in a Portuguese 50-year-old woman with CBS and in a family with progressive aphasia and behavioral features." (PMID 38203682, 2023).
Arterial thrombosis (1 paper, 2017). The formation of a blood clot inside an artery. "Acute stroke can occur in CBS deficiency patients due to arterial thrombosis/embolism and carotid artery disease/dissection but it is usually due to cerebral venous sinus thrombosis." (PMID 27778219, 2017).